SEZ6L (seizure related 6 homolog like)
Description:
May contribute to specialized endoplasmic reticulum functions in neurons.
Synonyms: SEZ6L1
Tractability: Antibody: UniProt predicts a signal peptide or a membrane-spanning region.
Gene: Protein-coding gene on chromosome 22 (26,169,462 to 26,383,597, forward strand). Ensembl gene ENSG00000100095.
Subcellular location: Endoplasmic reticulum membrane
Subcellular location (Human Protein Atlas): Vesicles
Gene Ontology:
Biological process: synapse maturation; adult locomotory behavior; cerebellar Purkinje cell layer development
Cellular component: endoplasmic reticulum; neuronal cell body; endoplasmic reticulum membrane
Genetic constraint (gnomAD): Loss-of-function variants: 33 observed, 98.09 expected, observed/expected ratio (o/e) 0.34, 90% interval 0.25 to 0.45. The upper end of that interval is the gene's LOEUF score, 0.45, which puts it in group 1 of 6, group 1 being the genes least tolerant of losing a copy. Missense variants: 1,111 observed, 1,312.1 expected, observed/expected ratio (o/e) 0.85, 90% interval 0.81 to 0.89. Synonymous variants: 508 observed, 560.63 expected, observed/expected ratio (o/e) 0.91, 90% interval 0.84 to 0.98.
Homologues: Orthologues: macaque SEZ6L (97% identical), chimpanzee SEZ6L (96% identical), pig SEZ6L (89% identical), dog SEZ6L (86% identical), rat Sez6l (81% identical), mouse Sez6l (80% identical), guinea pig SEZ6L (76% identical), tropical clawed frog sez6l (67% identical), zebrafish sez6l (53% identical). Paralogues in human: SEZ6 (40% identical), SEZ6L2 (39% identical), CSMD3 (22% identical), CSMD1 (22% identical), CSMD2 (21% identical), SVEP1 (18% identical), CR1 (14% identical), CR2 (13% identical), CFB (12% identical), C2 (11% identical), PAPPA2 (11% identical), C4BPA (10% identical), and 27 more.
Diseases named in the same sentence as SEZ6L in open-access papers:
SEZ6L is named in the same sentence as 31 diseases in open-access papers, as found by Europe PMC text mining. Sharing a sentence is not in itself a finding about the gene and the disease. The quoted sentences say what the papers report.
lung carcinoma (9 papers, 2014 to 2023). "Genetic analyses have implicated the loss of SEZ6L gene function in the risk for development of lung cancer by deletion, and in colon cancer through promoter hypermethylation." (PMID 35804849, 2022). "Although it has not previously been implicated in CRC, one study found an association between a genetic polymorphism in the SEZ6L gene and increased risk of lung cancer." (PMID 28522899, 2017). "Loss of normal function of SEZ6L could accelerate the progression of lung cancer and pancreatic cancer." (PMID 37701829, 2023). "Interestingly, deletions in the SEZ6L gene have been found in primary lung tumor cells, and loss-of-function variants in SEZ6L have been associated with increased risk of lung cancer." (PMID 33381488, 2020). "Similarly, the Liverpool Lung Project risk model improves its predictive capability of lung cancer by adding a marker SNP (rs663048) in the SEZ6L gene." (PMID 24787949, 2014). "SEZ6L plays a role in signal transduction and protein-protein interaction and increases in lung cancer." (PMID 35361267, 2022). "Testing the gene expression difference among patients with high-risk and low-risk score revealed a total of 14 genes with significant differences between the two groups, such as SEZ6L, IGFBP1, which are well-established to be implicated in lung cancer development." (PMID 35768804, 2022). "Loss of the normal function of seizure-related 6 homolog like (SEZ6L) could accelerate the progression of lung cancer." (PMID 35087823, 2021). "SEZ6L is also reported as a fusion gene in some lung cancers, melanoma and skin cancer." (PMID 33381488, 2020). "The other differentially expressed genes have been implicated in various other pathologies such as Peters' plus syndrome with cleft lip/palate (B3GALTL), tumor formation (COPZ2) and lung cancer development (SEZ6L) but have not yet been associated with tooth development." (PMID 25849153, 2015).
bipolar disorder (4 papers, 2016 to 2022). A disorder of the brain that causes unusual shifts in mood, energy, activity levels and the ability to carry out day-to-day tasks. "Variants of the SEZ6L gene are linked to distinct neuropsychiatric diseases, such as bipolar disorder and autism spectrum disorders, and also to cancer." (PMID 34958451, 2022). "SEZ6 has been genetically linked to febrile seizures and epilepsy, whereas SEZ6L was associated with bipolar disorder." (PMID 27716410, 2016). "Previously, polymorphisms in SEZ6L have also been associated with bipolar disorder including a gene x sex interaction, affecting susceptibility in women but not in men23, once again mirroring the results observed in our study animals with this polymorphism." (PMID 27685260, 2016). "Additional studies have also linked homologs of SEZ6, such as SEZ6L, to bipolar disorder." (PMID 34664540, 2022).
Alzheimer disease (3 papers, 2019 to 2021). A progressive, neurodegenerative disease characterized by loss of function and death of nerve cells in several areas of the brain leading to loss of cognitive function such as memory and language. "Remarkably, one of these genes, seizure related 6 homolog like is one of the physiological substrate of the β-secretase BACE1 (β-site APP cleaving enzyme), involved in the pathophysiology of Alzheimer’s disease and a drug target." (PMID 32742258, 2020).
autism spectrum disorder (3 papers, 2016 to 2022). A spectrum of developmental disorders that includes autism, and Asperger syndrome. "In humans, SEZ6L has recently been linked with autism spectrum disorder, which is a neurodevelopmental disorder connected with impairment in social interactions and communication." (PMID 27685260, 2016).
gastric cancer (3 papers, 2009 to 2022). A primary or metastatic malignant neoplasm involving the stomach. "SEZ6L encodes an adhesion-like type I membrane protein with unknown function associated with lung and gastric cancer." (PMID 19636377, 2009). "Promoter region methylation of SEZ6L gene was also clearly higher in gastric cancer tissue than in healthy gastric mucosa (50.5% vs. 29.3%)—however without statistical significance." (PMID 35885590, 2022). "Besides, CpG methylation of SEZ6L was increased in gastric cancer compared with non-neoplastic mucosa and played a carcinogenic role." (PMID 35087823, 2021).
schizophrenia (2 papers, 2018 to 2021). A major psychotic disorder characterized by abnormalities in the perception or expression of reality. "Interestingly, these genes have previously been associated with human social disorders such as autism for SEZ6L and schizophrenia for ARVCF." (PMID 30416887, 2018).
Anxiety (1 paper, 2022). Intense feelings of nervousness, tension, or panic often arise in response to interpersonal stresses. "In contrast, similar levels of anxiety were displayed by WT, SEZ6L het and SEZ6L KO mice as measured by their behaviour in the less aversive light-dark box test." (PMID 34958451, 2022). "Additionally, SEZ6L knockout mice displayed increased anxiety-like behaviour, although spatial learning and memory in the Morris water maze were normal." (PMID 34958451, 2022). "Future studies should further investigate the role of SEZ6L in anxiety-related behaviour and identify whether SEZ6L KO mice have enhanced fear learning, as identified in SEZ6 TKOs." (PMID 34958451, 2022). "We further demonstrate that the lack of SEZ6L is associated with anxiety-related behaviour, indicating that SEZ6L loss of function may contribute to aspects of neuropsychiatric diseases." (PMID 34958451, 2022). "In summary, our study establishes physiological functions for SEZ6L in regulating motor coordination and curbing anxiety-related behaviour, indicating that aberrant SEZ6L function in the human nervous system may contribute to movement disorders and neuropsychiatric diseases." (PMID 34958451, 2022). "In contrast, results from the elevated open field are comparable in SEZ6L KO and SEZ6 TKO mice, suggesting that SEZ6L deletion is contributing to the anxiety-like phenotype previously reported in SEZ6 TKO mice (which was also manifest in the zero maze, not examined in this study)." (PMID 34958451, 2022). "Taken together, the results of our study establish a physiological function for SEZ6L in motor coordination and a pathological contribution of the lack of SEZ6L to anxiety-related behaviour, implicating aberrant SEZ6L function in movement disorders and neuropsychiatric diseases." (PMID 34958451, 2022).
autism (1 paper, 2016). Persistent deficits in social interaction and communication and interaction as well as a markedly restricted repertoire of activity and interest as well as repetitive patterns of behavior. "Strikingly, four additional genes present in the same linkage blocks affect social abilities in humans, e.g., SEZ6L has been associated with autism and COMT affects aggression in adolescents with ADHD." (PMID 27685260, 2016).
ovarian carcinoma (1 paper, 2022). A malignant neoplasm originating from the surface ovarian epithelium. "Similar to what we observed in the early stage samples, CA125 and HE4 levels were elevated in the late stage ovarian cancer samples, while ITGAV and SEZ6L levels were higher in the healthy control samples." (PMID 35804849, 2022). "Interestingly, ITGAV and SEZ6L have not previously been identified as early stage ovarian cancer biomarkers, and the levels of both proteins were significantly decreased in sera from women with early stage ovarian cancer compared to healthy controls." (PMID 35804849, 2022).
prostate carcinoma (1 paper, 2025). A carcinoma that arises from epithelial cells of the prostate gland. "Overall, these data point to distinct epigenetic mechanisms of dysregulation of key prostate cancer biomarkers (GSTP1) including NE (ASCL1, SEZ6L), and luminal (e.g FOLH1) genes." (PMID 40593552, 2025).
tumor (9 papers, 2008 to 2022). "The effect of SAM to decrease methylation was proved to be beneficial in certain genes (HT-29: DTX1, GATA4, SEZ6L, TP53INP1; SW480: HAAO, TAL1), whose hypermethylation was associated with tumor progression according to the scientific literature." (PMID 32784836, 2020). "Other candidate tumor suppressor genes gene such as SLIT1, SEZ6L and MYO18B, were deleted in EOBRCA and consequently downregulated at the gene expression level, as reported in other solid tumors." (PMID 36352274, 2022). "A pattern of tumor profiling emerged: complete hypermethylation of SFRP1, SEZ6L, LPPH1 and CXX1 was common in CRC and gastric cancers, but only partial or no methylation was seen in all other types of cancer studied." (PMID 19424480, 2008). "Their findings suggested that SFRP1, SEZ6L, CXX1, KIAA0786, S100A10 and TIMP2 might influence tumor development and progression." (PMID 19424480, 2008). "Moreover, the presence of “anti-cancer” next to “pro-tumorigenic” within a single tumor only complicates the final conclusion regarding AP-2 role in that cancer (e.g. KRT14 vs GRIA1, SEZ6L, SLC12A5 for AP-2α within PAAD or NTSR1 vs PPEF1 for AP-2γ within LUAD)." (PMID 35361846, 2022). "Out of eleven genes, there was insufficient or no data for DPP6 or SEZ6L and NTSR1 in the tumor tissues for which they were identified throughout the study; thus, no comparison was possible." (PMID 35361846, 2022).
cancer (6 papers, 2016 to 2023). A tumor composed of atypical neoplastic, often pleomorphic cells that invade other tissues. "Using multiplex proteomic methods in urine samples, we identified four putative cancer-related proteins (FASLG, SEZ6L, LYPD3, and TFPI2) associated with arsenic exposure in women living around Lake Poopó, Bolivia." (PMID 33381488, 2020). "Using linear regression models adjusted for age, urinary osmolality, and urinary leukocytes, we identified associations between B-As and four putative cancer-related proteins: FASLG, SEZ6L, LYPD3, and TFPI2." (PMID 33381488, 2020). "Surprisingly, homologous structures, namely the CUB and SUSHI domains, are shared between CSMD1 and other proteins that play important roles in cancer progression, such as SEZ6L and DMBT1." (PMID 27756250, 2016). "The positive weights for CA125 and HE4 indicate a higher predicted likelihood of cancer for those with a higher expression, while the negative weights for ITGAV and SEZ6L indicate a lower predicted likelihood of cancer for those with a higher expression." (PMID 35804849, 2022).
bone disorder (1 paper, 2024). "Notably, genes such as CSRP2, DDX1, RHBDL1, SEZ6L, and CTSK are involved in growth, development, locomotion, and bone disorders." (PMID 38788487, 2024).
SEZ6L also shares sentences with these, for which no sentence is quoted: cognitive deficits (2 papers); cardiomyopathies (1); Cerebral ischemia (1); colon cancer (1); colorectal cancer (1); epilepsy (1); ischemic heart disease (1); lip (1); melanoma (1); movement disorder (1); neurodevelopmental disorder (1); neurological diseases (1); Niemann-Pick type C disease (1); Obesity (1); pancreatic cancer (1); Peters plus syndrome (1); preeclampsia (1); skin cancer (1).